IL6 (interleukin 6)
Diseases named in the same sentence as IL6 in open-access papers (continued):
Sharing a sentence is not in itself a finding about the gene and the disease.
thymoma (5 papers, 2010 to 2024). A neoplasm arising from the epithelial cells of the thymus. "A very recent study demonstrated increased levels of IL-6 in patients with MG and thymoma compared to patients with thymoma alone, thus suggesting its association with MG and its potential role in Treg cell decrease." (PMID 36059463, 2022). "To evaluate the possible association of increased CRP serum concentrations with proinflammatory cytokines we measured IL-6 and IL-1β serum concentrations in 39 patients with TETs (thymoma: n = 23; TC: n = 15) in comparison to age- and sex-matched volunteers." (PMID 28514756, 2017). "Three of the anti‐IL‐6 positive thymoma patients also had autoantibodies against IFN‐α2a, IL‐17s, and/ or IL‐22." (PMID 27957331, 2016). "Pre‐incubating positive APECED or thymoma patients’ sera with recombinant human (rh) IL‐6 completely blocked subsequent binding to IL‐6 in LIPS assays (p < 0.01), whereas a control cytokine, rhIL‐IFN‐γ, had no such effect (p > 0.05)." (PMID 27957331, 2016). "Sera from patients with APECED or thymomas and healthy controls were tested for autoantibodies against IL‐6, IL‐1β, IL‐21, IL‐23 (p19 + p40), or TGF‐β3 using LIPS assays that preserve the natural cytokine conformations." (PMID 27957331, 2016). "We found autoantibodies binding to conformational epitopes of IL‐6 in 19.5% of 41 patients with APECED and 12.5% of 104 with thymoma—especially in those with long disease durations." (PMID 27957331, 2016). "Taken together, IL‐6 was the only Th17‐driving cytokine that was recognized by autoantibodies in both APECED and thymoma patients." (PMID 27957331, 2016). "In conclusion, we found autoantibodies binding IL‐6 in some long‐duration APECED and thymoma patients, and autoantibodies to IL‐23 that cross‐reacted with IL‐12 in thymoma patients." (PMID 27957331, 2016). "Like the autoantibodies against type I IFNs, Th17 cytokines and/or some organ‐specific auto‐antigens 8, those against IL‐6 were shared between APECED and thymoma patients, but were found later in the disease course and much less frequently." (PMID 27957331, 2016). "In this study, we showed that among Th17‐driving cytokines, only IL‐6 was recognized by autoantibodies in some APECED and thymoma patients, and IL‐23 in some thymoma patients." (PMID 27957331, 2016). "Altogether, there were too few anti‐IL‐6 positive APECED and thymoma patients to justify correlations with other demographic or clinical parameters or tumor histology." (PMID 27957331, 2016). "Luciferase immunoprecipitation (LIPS) was used to screen for autoantibodies to IL‐6, IL‐1β, TGF‐β3, IL‐21, and IL‐23 in patients with APECED or thymoma." (PMID 27957331, 2016). "Disparately from these previous studies, the IL‐6 autoantibodies we detected in our APECED and thymoma patients were probably targeted to different—more conformation‐sensitive—epitopes: even adsorption to plastic abolished the binding as well as unfolding in SDS buffer." (PMID 27957331, 2016). "As expected, other infections were common in the thymoma patients, many of whom were taking corticosteroids for their MG, but, again, they did not clearly co‐occur with the IL‐6 antibodies." (PMID 27957331, 2016).
torsades de pointes (5 papers, 2018 to 2025). A malignant form of polymorphic ventricular tachycardia that is characterized by heart rate between 200 and 250 beats per minute, and qrs complexes with changing amplitude and twisting of the points. "Previous studies demonstrated that circulating IL-6 levels are elevated in patients with autoimmune-inflammatory disorders and may underlie increased vulnerability to QT interval prolongation that contributes prominently to arrhythmic events and Torsade de Pointes (TdP)." (PMID 30521586, 2018).
tularemia (5 papers, 2011 to 2025). Tularemia is an infection caused by the bacterium Francisella tularensis. "However, TNF-/-, IL-6-/- and Casp1/11-/- mice are more susceptible to pulmonary tularemia and, demonstrating the essential role of these cytokines in tularemia." (PMID 27015566, 2016). "Later in pulmonary tularemia, the release of inflammatory cytokines (IL-1β, IL-6, TNFα, etc.)and DAMPs/alarmins (e.g. HMGB1, S100A9) are suggested ‘drivers’ of host death." (PMID 27015566, 2016). "Serum levels of eotaxin, G-CSF, IFNα, IFNγ, IL-1β, IL-2, IL-6, IL-8, IL-10, IP-10, MCP-1, MIP-1α, MIP-1β, and PDGF were significantly increased in tularemia patients when compared to healthy controls and/or between different time points of sampling." (PMID 33114188, 2020). "GSK3 inhibition reduced IL-12p40, IL-6 and TNF-α in a mouse model of tularemia." (PMID 21483672, 2011). "Host cell recognition of and response to released mitochondria and other damage-associated molecular patterns engenders a sepsis-like syndrome typified by production of TNF, IL-1β, IL-6, IL-12p70, and IFN-γ during late-phase tularemia (⩾72 h), but are absent early during infection." (PMID 28955505, 2017).
urothelial bladder cancer (5 papers, 2016 to 2024). "Preoperative plasma levels of Interleukin 6 (IL6) and its soluble receptor (IL6sR) have previously been associated with oncologic outcomes in urothelial carcinoma of the bladder (UCB); however, external validation in patients treated with radical cystectomy (RC) for UCB is missing." (PMID 34023914, 2022). "The differences between the two strains are also related to a different modulation in T24 (human urinary bladder transitional cell carcinoma) cells of inflammation mediators such as pro-inflammatory cytokines IL-6, IL-8 and IL-1β and the anti-inflammatory cytokine TGF-β." (PMID 28212280, 2017). "Additionally, IL-6 and IL-8 were increased in sera of patients affected with urothelial bladder cancer." (PMID 26927195, 2016). "For example, FOXQ1 expression inhibited activation of the IL6/JAK/STAT3 signaling pathway, IL2/STAT5 signaling pathway, allograft rejection pathway, apical junction pathway, and complement pathway in bladder urothelial carcinoma." (PMID 36118871, 2022).
uterine fibroids (5 papers, 2020 to 2025). "Inflammation plays a critical role in the development of uterine fibroids, characterized by elevated expression levels of pro-inflammatory and inflammatory cytokines such as interleukin-1, interleukin-6, interleukin-10, TNF-α, and TGF-β." (PMID 39911698, 2025). "In line with this, in uterine fibroids, the phagocytic ability of neutrophils is affected by the serum levels of IL-2, IL-17A, IL-6, and IL-4." (PMID 40943781, 2025). "Human uterine leiomyoma (HuLM) cells responded more to leptin treatment compared to myometrium cells with increased secretion of inflammatory factors: IFNγ, IL-6, IL-8, MCP-1, GM-CSF, and TNF-a." (PMID 36771423, 2023). "Both primary and secondary TFI groups showed significantly elevated levels of TNF-α, IL-8, IL-6, and TGF-β1 in the peritoneal fluid as compared to patients with uterine fibroids." (PMID 33092547, 2020). "Compared to the patients with uterine fibroids, patients with secondary TFI showed significantly higher levels of TNF-α, IL-8, IL-6, and TGF-β1 in the serum samples, whereas the serum cytokine concentrations were not statistically significant between patients with primary TFI and the control group." (PMID 33092547, 2020). "The results of the present study revealed that the serum levels of TNF-α, IL-8, IL-6, and TGF-β1 were higher in the secondary group than in the uterine fibroids group, and the differences in the levels of TNF-α, IL-6, IL-8 and TGF-β1 in serum between these two groups were statistically significant." (PMID 33092547, 2020). "Therefore, according to the results of our studies, IL-6 does not appear to play a role in the development of uterine fibroids." (PMID 40672945, 2025).
ventricular fibrillation (5 papers, 2017 to 2025). A disorder characterized by an electrocardiographic finding of a rapid grossly irregular ventricular rhythm with marked variability in QRS cycle length, morphology, and amplitude. "IL-6 is closely linked to ventricular tachycardia (VT), ventricular fibrillation (VF), and SCD." (PMID 38327491, 2024). "Elevated IL-6 serum levels are correlated with the occurrence of spontaneous ventricular tachyarrhythmia and ventricular fibrillation in implantable cardioverter-defibrillator (ICD)-recipient patients with CAD and idiopathic dilated cardiomyopathy." (PMID 35402550, 2022). "Inflammatory cytokines (such as TNF-α, IL-6, IL-1β, IL-17) are involved in the pathogenesis of malignant VAs (ventricular tachycardia (VT) and ventricular fibrillation (VF)), but are largely overlooked in the management of heart rhythm disorders." (PMID 41574188, 2025).
ventricular tachycardia (5 papers, 2016 to 2025). A disorder characterized by an electrocardiographic finding of three or more consecutive complexes of ventricular origin with a rate greater than a certain threshold (100 or 120 beats per minute are commonly used). "The results of fundamental and clinical studies have demonstrated the association of pro-inflammatory cytokines, mainly IL-6, with the risk of developing long QT syndrome and ventricular tachycardia." (PMID 36611412, 2022). "Along with TNF and IL-6, IL-1 (not mature IL-1β) was indicated as a factor involved in delayed repolarization, long QT syndrome, and ventricular tachycardia." (PMID 36341442, 2022). "Indeed, mice that underwent thoracotomy did not exhibit greater ventricular tachycardia inducibility compared with sham mice, consistent with the lack of macrophage-dependent IL-6Rα production and subsequent IL-6 transsignaling." (PMID 40048254, 2025).
xerostomia (5 papers, 2021 to 2023). Dryness of the mouth resulting from reduced salivary secretion. "Salivary cortisol, TNF-α, and IL-6 were measured in three RCTs; oral salivary flow rate was examined in two RCTs; and the association between xerostomia and BMS was investigated in one RCT." (PMID 37814265, 2023). "Cytokines such as interleukin (IL)-1 beta (IL-1β), IL-6, IL-8, and tumor necrosis factor (TNF) have been linked to oral mucositis, and possibly xerostomia, during RT, manifested by elevated levels in saliva immediately after treatment in HNC patients." (PMID 36350483, 2022). "Among the inflammatory cytokines assessed - IL-6, TNF-α, IFN-γ, IL-10, IL-12p70, IL-1β, IL-8, IL-13, IL-2, IL-5, IL-7 and IL-17A, xerostomia correlated with lower levels of saliva IL-2 and TNF-α, and elevated levels of serum IL-12p70 and IL-10 (p < 0.05)." (PMID 36846089, 2023). "We did not observe any associations between levels of IL-6, IL-8, IP-10, TARC, TNF, and ENA-78 in the HNC survivors who reported xerostomia, dysphagia, and CF scores above thresholds, and those who did not." (PMID 36350483, 2022).
Yersinia infection (5 papers, 2018 to 2024). "LFchimera induced stimulation of IL-8 expression by Yersinia infected cells and exhibited a direct effect on the stimulation of IL-6 expression, independent from Yersinia infection." (PMID 30136243, 2018). "In contrast, caspase-8 promotes TLR4-induced NF-κB activation in mouse B cells independent of its protease enzymatic activity, whereas the production of inflammatory cytokines (TNF, IL-6, IL-12) upon Yersinia infection relies on the protease enzymatic activity of caspase-8." (PMID 38789425, 2024).
Achalasia (4 papers, 2019 to 2025). A disorder of esophageal motility characterized by the inability of the lower esophageal sphincter to relax during swallowing and by inadequate or lacking peristalsis in the lower half of the body of the esophagus. "The statistical comparisons between the different biomarker profiles of patients with achalasia, EoE, and GERD revealed statistically significant increases in IL-6 (p 0.05) in the achalasia group vs. EoE group." (PMID 30744559, 2019). "A review of the literature suggests that TNF-α, IL-6, IFN-γ, IL-12, IL-17, IL-22, and IL-23 theoretically could contribute to the underlying etiology of achalasia." (PMID 30744559, 2019). "Another study compared the plasma immunological profiles of TNF-α, IL-6, IFN-γ, IL-12, IL-17, IL-22 and IL-23 in 53 patients with achalasia, 22 eosinophilic esophagitis (EoE), and 20 gastroesophageal reflux disease, through Quantikine Human Immunoassays." (PMID 39337632, 2024). "In this study, we investigated plasma biomarker levels of IL-6, IL-12p70, IL-17, IL-22, IL-23, TNFα and INF-γ in patients with achalasia, EoE, and GERD." (PMID 30744559, 2019). "The primary aim of our study was to compare the plasma immunological profiles of plasma of TNF-α, IL-6, IFN-γ, IL-12, IL-17, IL-22, and IL-23 in patients with achalasia, EoE, and GERD." (PMID 30744559, 2019).
Acidosis (4 papers, 2020 to 2025). Abnormal acid accumulation or depletion of base. "Acidosis induces IL-6 expression, secretion, and biological effects, with p38 kinase as a crucial mediator." (PMID 40217316, 2025). "Acidosis decreased the gene expression of the pro-inflammatory markers Nos2, Ccl2, and IL-6 in IFN-γ/lipopolysaccharide-polarized macrophages, and it increased the expression of anti-inflammatory markers CD206 and Arg1 in IL-4-polarized macrophages." (PMID 32823915, 2020). "Acidosis-induced RASF elevates the transcription levels of numerous cytokines, encompassing classical innate immune cell chemotactic combinations such as CCL2, IL8, and CCL5, along with inflammatory cytokine combinations like IL6 and IL12, which are contingent upon adaptive immune responses." (PMID 40234753, 2025).
acromegaly (4 papers, 2020 to 2024). Acromegaly is an acquired disorder related to excessive production of growth hormone (GH) and characterized by progressive somatic disfigurement (mainly involving the face and extremities) and systemic manifestations. "A prospective study involving 31 patients with active acromegaly compared to 25 healthy controls showed that TNF-α, IL-6, and activin-A were elevated in patients with active acromegaly compared to controls." (PMID 37584889, 2024). "Circulating IL-6 concentrations have been reported to be similar in healthy controls and patients with either active or controlled acromegaly." (PMID 32458292, 2020). "In our study, the serum IL-6 concentrations were significantly higher in acromegaly patients than controls." (PMID 33154456, 2020). "A significant increase in serum IL-6 (p = 0.019) and TGF-β1 (p = 0.025) levels was observed in patients with acromegaly compared to controls." (PMID 33154456, 2020).
acute B lymphoblastic leukemia (4 papers, 2020 to 2025). "In studies, patients with B-cell lymphoblastic leukemia following CAR-T cell therapy presented elevated levels of IL-1α, IL-2, IL-3, IL-5, IL-6, IL-8 IL-10, IL-15, IFN- γ, procalcitonin, CRP, G-CSF, GM-CSF, and MCP-1, and their levels were linked to the severity of neurotoxicity." (PMID 39409959, 2024).
Acute encephalopathy (4 papers, 2018 to 2022). "Some studies have shown that serum IL-6, IL-10, and TNF-α levels were elevated in KD, and these cytokines could cause brain damage in acute encephalopathy following prolonged febrile seizures." (PMID 31922014, 2018). "Here, we retrospectively investigated levels of serum PCT, C-reactive protein (CRP), and inflammatory cytokines (IL-6, TNF-α, and IFN-γ) in the second phase of patients with acute encephalopathy with biphasic seizures and late reduced diffusion (AESD)." (PMID 29725488, 2018).
Acute otitis media (4 papers, 2011 to 2022). Acute otitis media is a short and generally painful infection of the middle ear. "In perforated acute otitis media (AOM) exudates containing live bacteria, IL-6 and IL-8 were also detected in high amounts." (PMID 34575515, 2021).
acute pharyngitis (4 papers, 2020 to 2025). An acute and painful inflammatory process that affects the pharynx. "IL-6 activates mononuclear macrophages and impacts immune responses, whereas IL-1β overexpression causes tissue damage, edema, and exacerbate responses in rats with acute pharyngitis through interactions with TNF-α and IL-6." (PMID 41357871, 2025). "In the experimental studies assessing the pharmacological effects of KHJ on acute pharyngitis before and after compatibility, all drug groups exhibited significant reductions in serum IL-1β, IL-6, and PGE2 levels, besides a notable increase in IL-10 levels." (PMID 41357871, 2025). "In order to assess the impact of TR on the inflammatory response in AP rats, inflammatory cytokines closely associated with acute pharyngitis, such as TNF-α and IL-6, were measured." (PMID 39568590, 2024). "In support, a recent study applying a rabbit model of acute pharyngitis revealed that the anti-inflammatory effects of resveratrol were due to down-regulated caspase-3 expression and decreased IL-6 and TNF-α serum levels." (PMID 33255723, 2020). "Our initial exploration revealed that TR treatment for acute pharyngitis engages targets such as PIK3CA, IL6, AKT1, TNF, PTGS2/COX-2, among others." (PMID 39568590, 2024). "Subsequently, the mRNA expressions of IL-6, TNF-α, and COX-2 were evaluated in the pharyngeal tissue of acute pharyngitis rats." (PMID 39568590, 2024). "Moreover, Resveratrol showed potent anti-inflammatory activity as lowered NF-κB, TNF-α, and IL-6 serum levels, as well as COX-2 activity and reactive oxygen species production in an animal model of acute pharyngitis." (PMID 32423112, 2020).
advanced heart failure (4 papers, 2016 to 2024). Patients with advanced heart failure have severe limitations, experiences symptoms even while at rest and are mostly bedbound patients. "Elevated expression of myocardial IL-6 in advanced heart failure could be contributing to this process." (PMID 27884156, 2016).
aging (4 papers, 2022 to 2025). A developmental process that is a deterioration and loss of function over time. "COX-2, IL-1, and IL-6 are pro-inflammatory mediators that play a major role in causing skin aging and inflammatory skin symptoms." (PMID 35204307, 2022). "IL6, a pro-inflammatory cytokine frequently elevated during skin aging, acts as a major mediator of age-related inflammatory processes." (PMID 41516153, 2025). "The key cytokines involved in the pathogenesis of skin aging included interleukins such as IL-6, COL-I, TNF-α, and IL-1β." (PMID 40872627, 2025).
agranulocytosis (4 papers, 2020 to 2025). "We recommend using JAK inhibitors and IL-6 receptor blockers with caution in patients at high risk of severe infection and agranulocytosis, and the combination of JAK inhibitors and IL-6 reporter blockers should be used under strict trade-offs." (PMID 38264533, 2023). "The PPI and KEGG enrichment pathway analyses demonstrated that clozapine induces agranulocytosis by modulating the hematopoietic cell lineage and JAK–STAT signaling pathways via interleukin‐3 (IL3), IL6, IL2 receptor subunit alpha (IL2RA), and granulocyte colony‐stimulating factor." (PMID 39776289, 2025).
anaplastic thyroid cancer (4 papers, 2013 to 2025). "It has previously been shown that IL-6, in the human anaplastic thyroid cancer HTh74 and HTh74R (doxorubicin-resistant) cell lines, did not significantly affect cell viability (in MTT assay), but augmented colony formation." (PMID 36551653, 2022).
angiosarcoma (4 papers, 2010 to 2025). A malignant tumor arising from the endothelial cells of the blood vessels. "IL8 and IL6, both of which were enriched in our hemangiosarcoma samples, are recurrently associated with inflammation that "benefits" tumors, and PTGS2 (a.k.a., COX-2) is the single most common tumor-associated pro-inflammatory mediator." (PMID 21062482, 2010). "In these models, animals developed angiosarcoma in the lung, liver, and spleen and systemic inhibition of Ikkβ, IL-6 or STAT3 significantly inhibited angiosarcoma growth." (PMID 27105514, 2016). "VEGF, MMP-9, and IL-6 are highly expressed by hemangiosarcoma tumor cells, suggesting that hemangiosarcomas use these factors to alter their tumor microenvironment (TME) and promote tumor growth." (PMID 29061946, 2015).